CD63-AS1 (CD63 antisense RNA 1)
Synonyms: CEAM
Gene: Long non-coding RNA gene on chromosome 12 (55,729,078 to 55,730,857, forward strand). Ensembl gene ENSG00000258056.
Diseases named in the same sentence as CD63-AS1 in open-access papers:
CD63-AS1 is named in the same sentence as 3 diseases in open-access papers, as found by Europe PMC text mining. Sharing a sentence is not in itself a finding about the gene and the disease.
CD63-AS1 shares sentences with these, for which no sentence is quoted: Anxiety (1 paper); mesonephric adenocarcinoma (1); serous carcinoma (1).